RSPO1 (R-spondin 1)
Description:
Activator of the canonical Wnt signaling pathway by acting as a ligand for LGR4-6 receptors. Upon binding to LGR4-6 (LGR4, LGR5 or LGR6), LGR4-6 associate with phosphorylated LRP6 and frizzled receptors that are activated by extracellular Wnt receptors, triggering the canonical Wnt signaling pathway to increase expression of target genes. Also regulates the canonical Wnt/beta-catenin-dependent pathway and non-canonical Wnt signaling by acting as an inhibitor of ZNRF3, an important regulator of the Wnt signaling pathway. Acts as a ligand for frizzled FZD8 and LRP6. May negatively regulate the TGF-beta pathway. Has a essential roles in ovary determination. Regulates Wnt signaling by antagonizing DKK1/KREM1-mediated internalization of LRP6 through an interaction with KREM1.
Synonyms: FLJ40906; RSPONDIN; CRISTIN3; RSPO
Tractability: Small molecule: a structure with a bound ligand is known. Antibody: UniProt places it where antibodies can reach, with high confidence; its Gene Ontology location is reachable by antibodies, with high confidence; UniProt predicts a signal peptide or a membrane-spanning region.
Gene: Protein-coding gene on chromosome 1 (37,610,802 to 37,635,604, reverse strand). Ensembl gene ENSG00000169218.
Subcellular location: Secreted; Nucleus
Subcellular location (Human Protein Atlas): Vesicles; Predicted to be secreted
Pathways (Reactome):
Signal Transduction: Regulation of FZD by ubiquitination
Gene Ontology:
Molecular function: G protein-coupled receptor binding; protein binding; signaling receptor binding
Biological process: positive regulation of canonical Wnt signaling pathway; positive regulation of protein phosphorylation; positive regulation of Wnt signaling pathway; regulation of receptor internalization
Cellular component: extracellular region; non-collagenous component of interstitial matrix; nucleus
Genetic constraint (gnomAD): Loss-of-function variants: 20 observed, 28.92 expected, observed/expected ratio (o/e) 0.69, 90% interval 0.49 to 1. The upper end of that interval is the gene's LOEUF score, 1, which puts it in group 4 of 6, group 1 being the genes least tolerant of losing a copy. Missense variants: 309 observed, 368.37 expected, observed/expected ratio (o/e) 0.84, 90% interval 0.76 to 0.92. Synonymous variants: 133 observed, 143.92 expected, observed/expected ratio (o/e) 0.92, 90% interval 0.8 to 1.07.
Homologues: Orthologues: chimpanzee RSPO1 (99% identical), pig RSPO1 (92% identical), dog RSPO1 (90% identical), macaque RSPO1 (90% identical), mouse Rspo1 (89% identical), guinea pig RSPO1 (87% identical), rat Rspo1 (87% identical), tropical clawed frog rspo1 (54% identical), zebrafish rspo1 (50% identical). Paralogues in human: RSPO3 (43% identical), RSPO2 (37% identical), RSPO4 (35% identical).
Diseases named in the same sentence as RSPO1 in open-access papers:
RSPO1 is named in the same sentence as 109 diseases in open-access papers, as found by Europe PMC text mining. Sharing a sentence is not in itself a finding about the gene and the disease. The quoted sentences say what the papers report.
colon carcinoma (20 papers, 2009 to 2024). "Among them, RSPO1 was associated with the cancer phenotype of palmoplantar keratosis and showed metastasis-related features in colon cancer." (PMID 39720726, 2024). "In the present study we determined the affinity and potency of LGR6 for RSPO1–4 in potentiating Wnt/β-catenin signaling, and characterized the activity of three mutations identified in colon cancer samples." (PMID 22615920, 2012). "These included an ovarian tumor with RSPO1, pancreatic and colon tumors with RSPO2, and lung and CRC tumors with RSPO3 overexpression." (PMID 34663878, 2021). "It adds to previous reported Wnt/β-catenin independent role of Rspo1 in antagonizing colon cancer metastasis, in which LGR5 directly binds to TGFβ receptors for the activation of TGFβ signaling." (PMID 32749219, 2020). "In colon cancer, R-spondin 1 and R-spondin 2 have been demonstrated to suppress CRC tumorigenesis and progression via Wnt-dependent or-independent mechanisms." (PMID 30337838, 2018). "In a mouse xenograft model of human colon carcinoma, CT26, treatment with Rspo1 reduced the mucositis, diarrhea and weight loss caused by the chemotherapeutic agent, 5-flurouracil (5-FU), without affecting its antitumor effect." (PMID 19956666, 2009). "Interestingly, some studies showed that RSPO1 can suppress colon cancer metastasis by activating TGFβ signaling." (PMID 38962149, 2024). "RSPO1 stimulation of LGR4 potentiates Wnt signaling which is generally oncogenic, and overexpression of RSPO2 and RSPO3 is associated with carcinogenesis in human colon cancer as well as in mouse models of breast and colon cancer." (PMID 24205130, 2013). "To understand potential roles and mechanisms of LGR6 in oncogenesis, we profiled a panel of colon cancer and uterine cancer cell lines for expression levels of LGR4–6 and RSPO1–4." (PMID 22615920, 2012). "RSPO1/Lgr5 axis activates Wnt/β-catenin signaling and promotes EMT and tumor formation in breast cancer and glioblastoma whilst, by enhancing TGFβ-mediated growth inhibition and stress-induced apoptosis, it suppresses metastasis in colon cancer." (PMID 35854363, 2022).
colitis (10 papers, 2009 to 2025). Inflammation of the colon. "In addition, systemic administration of Rspo1 decreased inflammation and reduced the loss of body weight, diarrhea and rectal bleeding in a mouse model of dextran sulfate sodium-induced colitis." (PMID 19956666, 2009). "Systemic administration of Rspo1 decreased the histological and clinical manifestations of dextran sulfate sodium-induced colitis as well as chemotherapy- and radiation-induced oral mucositis in mice." (PMID 25865226, 2015). "Rspo1 has also been shown to ameliorate colitis in mice by improving the mucosal integrity of the gut." (PMID 24628794, 2014). "Furthermore, systemic administration of Rspo1 decreased the histological and clinical manifestation of dextran sulfate sodium-induced colitis and chemotherapy and radiation-induced oral mucositis in mice." (PMID 19956666, 2009). "As a potent regenerative agent, the R-spondin 1 protein (Rspo1) has been reported to promote repopulation of the mouse intestinal epithelium, resulting in the amelioration of inflammatory symptoms in not only DSS-induced experimental mice but also IL-10-deficient colitis model mice." (PMID 34835369, 2021). "Importantly, the protective role of SIRT6 in colitis maybe mediated by R-spondin-1 because SIRT6 fails to prevent proinflammatory cytokines induced YAMC (a normal colonic epithelial cell line) cell death when Rspo1 is silenced by siRNA27." (PMID 36057627, 2022).
ovarian carcinoma (10 papers, 2018 to 2024). A malignant neoplasm originating from the surface ovarian epithelium. "Also, SNPs in the RSPO1 locus have been identified as risk factors for ovarian cancers of serous histology." (PMID 34663878, 2021). "RSPO1 was found to be highly expressed in ovarian cancer cells and tissues and modulated ovarian cancer biological activity by activating Wnt/β-catenin signaling." (PMID 38183076, 2024). "The downregulation of RSPO1 prevented the proliferation and migration of ovarian cancer cells, and induced apoptosis." (PMID 36645115, 2023). "illustrated that the transcription and protein expression of RSPO1 in ovarian cancer cell lines and tissues were upregulated compared with normal samples." (PMID 36645115, 2023). "RSPO1 is an upstream regulator in the Wnt/β-catenin pathway, which can help ovarian cancer cells grow, survive, and migrate." (PMID 36645115, 2023). "Considering RSPOs in ovarian cancer, in silico analysis suggested relatively high RSPO1 mRNA expression in ovarian cancer, and another study reported high expression of RSPO1 and RSPO3 in ovarian tumor xenograft material." (PMID 34663878, 2021). "When either TNKS or RSPO1 are inhibited, Wnt/β-catenin signaling activity decreases and ovarian cancer cells undergo apoptosis." (PMID 32560059, 2020). "Developing theranostic approaches that capitalize on DKK1 and RSPO1 as therapeutic targets may pave the way for personalized treatment strategies tailored to the unique molecular profiles of ovarian cancer patients." (PMID 40836974, 2024). "However, in human disease, RSPO1 was found to promote progression in ovarian cancer by increasing the proliferation and migration of ovarian cancer cells and reducing ovarian cancer cells’ apoptosis." (PMID 35886859, 2022). "Similarly independent of Wnt ligands, RSPO1 promotes ovarian cancer cell survival and migration through upstream activation of the Wnt/β-catenin signaling pathway." (PMID 32560059, 2020).
breast cancer (8 papers, 2011 to 2025). A primary or metastatic malignant neoplasm involving the breast. "Our results add the prognostic significance of RSPO1 to its previous association with breast cancer." (PMID 24373193, 2013). "RSPO1 upregulates the expression of Esr1 and ERα signaling targets Pgr and Greb1 (growth regulation by estrogen in breast cancer 1) in a dose-depending manner." (PMID 32749219, 2020). "In normal breast tissue of healthy women, RSPO1 was upregulated in the high serum estrogen level group and downregulated in the breast cancer group." (PMID 24373193, 2013). "Six of the genes (CASP1, CCL2, ADGRE5, IL3RA, RSPO1, and STAB1) are co‐expressed with the CH25H gene in both cancers, while two genes (ANPEP in breast cancer and CCL8 in prostate cancer) are exclusively co‐expressed with the CH25H gene in one of the tumors." (PMID 41159143, 2025). "In an ESR1-luciferase reporter assay using T47D (a human breast cancer cell line), LGR4 knockdown also inhibited the luciferase activities induced by RSPO1." (PMID 32749219, 2020).
adenoma (7 papers, 2020 to 2025). A neoplasm arising from the epithelium. "added RSPO1 to mice models and found that the number of adenoma organoids in mice decreased significantly and interfered with the expression of Wnt target genes." (PMID 36645115, 2023).
liver fibrosis (6 papers, 2017 to 2026). "Previously RSPO1 and 2 were reported to be up-regulated in a CCl4-induced liver fibrosis model, however, the biological consequence of RSPO1 and RSPO2 expression has not been described." (PMID 32160239, 2020). "We next tested anti-RSPO1, 2, and 3 antibodies in vivo in a CCl4-induced mouse model of liver fibrosis with prophylactic dosing." (PMID 32160239, 2020). "To investigate a potential role for RSPO proteins in fibrosis, we began by examining the expression of RSPO 1, 2 and 3 in CCl4-induced liver fibrosis by immunohistochemistry (IHC)." (PMID 32160239, 2020). "Factors like HGF and/or Rspo1 have been shown to promote expansion of these LGR5 + cells and attenuate liver fibrosis in mice." (PMID 37798809, 2023). "We observe Lgr5+ liver stem cells in human liver fibrosis tissues, and once they are isolated, these cells are able to form organoids, and treatment with HGF/Rspo1 promotes their expansion." (PMID 29079780, 2017). "Moreover, Lgr5+ liver stem cells were isolated from human liver fibrosis tissues, and single human Lgr5+ liver cells expanded as organoids, which could be further enhanced by treatment with HGF and Rspo1 proteins in vitro." (PMID 29079780, 2017). "However, in our studies, Rspo1 injections did not facilitate liver fibrosis in vivo with or without CCL4 damage (and data not shown)." (PMID 29079780, 2017).
Obesity (6 papers, 2019 to 2024). Accumulation of substantial excess body fat. "Here, the authors screen all Wnt‐related paracrine factors in 1994 obese cases and 2161 controls using whole‐exome sequencing (WES) and identify that 12 obese patients harbor the same mutations in RSPO1 (p.R219W/Q) predisposing to human obesity." (PMID 36755192, 2023). "To further establish the effects of RSPO1 p.R219W mutation on obesity in vivo, we thus produced a p.R219W point mutation knock‐in mouse model using the CRISPR–Cas9 approach, to recapitulate the homologous mutation that occurs in humans faithfully." (PMID 36755192, 2023). "This study identifies a gain‐of‐function RSPO1 mutation (p.R219W) that acts as a genetic trigger to drive obesity in response to HFD feeding and reveals the possible etiology of human RSPO1 mutation in repressing thermogenic capacity by disrupting its electrostatic binding to ECM." (PMID 36755192, 2023). "In addition, we observed more pronounced weight gain and thermogenesis suppression in female Rspo1R219W mice compared with wild‐type mice, but no significant changes were observed in male mice, indicating a possible sex‐by‐genotype interaction between RSPO1 p.R219W mutation and obesity." (PMID 36755192, 2023). "Thus, gain‐of‐function mutations in the RSPO1 gene confer a risk for human obesity." (PMID 36755192, 2023). "Mice overexpressing human RSPO1 in adipose tissues develop obesity under a high‐fat diet (HFD) due to reduced brown/beige fat thermogenesis." (PMID 36755192, 2023). "Based on the in vivo and in vitro experimental results, we established RSPO1 as an essential suppressor of fat thermogenesis whose overexpression promotes HFD‐induced obesity." (PMID 36755192, 2023). "To further investigate the potential anti‐obesity effect of blocking endogenous Rspo1, we generated Rspo1 knockout (Rspo1−/−) mice and confirmed that endogenous Rspo1 was effectively deleted in Rspo1−/− mice." (PMID 36755192, 2023). "A recent study reported that RSPO1/LGR4 axis was involved in obesity-related renal fibrosis through promoting Wnt/β-catenin signaling pathway, providing a potential therapeutic target for the obesity-related chronic kidney disease (CKD)." (PMID 35140734, 2021). "It has been found that circulating RSPO1 was remarkably elevated in patients with obesity and insulin resistant." (PMID 35082683, 2021). "RSPO1 levels also presented a positive correlation with both obesity and insulin resistance." (PMID 37955008, 2023). "Artificially overexpressing human RSPO1 in fat tissues also resulted in similar obesity phenotypes." (PMID 36755192, 2023). "Importantly, genetic ablation of Rspo1 robustly increases the thermogenic capacity of visceral fat and resists HFD‐induced obesity in vivo, indicating the underlying therapeutic potential to treat obesity by blocking RSPO1 signaling in adipose tissues." (PMID 36755192, 2023). "Blocking RSPO1 signals promotes mitochondrial respiration and thermogenesis and reduces adiposity, highlighting its pivotal therapeutic implications for treating human obesity." (PMID 36755192, 2023). "A high level of RSPO1 is responsible for the development of obesity and insulin resistance." (PMID 30678306, 2019). "RSPO1 is a novel serum marker of obesity and may have a role in adipocyte beiging as well." (PMID 38702075, 2024). "To investigate whether increased RSPO1 in adipose tissue can induce obesity, we generated an aP2 promoter‐driven human RSPO1 (hRSPO1) transgenic mouse model (hRSPO1Tg) in which hRSPO1 was effectively overexpressed in three adipose tissues." (PMID 36755192, 2023).
lung carcinoma (5 papers, 2017 to 2023). "used ONCOMINE analysis to illustrate the expression levels of RSPO1, 2, and 3 mRNAs in lung cancer tissues and found that they were notably lower than those in normal samples." (PMID 36645115, 2023). "MYOCD, RSPO1 and ARHGAP20 have all been implicated in various cancers, including lung cancer." (PMID 32899298, 2020). "For instance, the expressions of RSPO1, RSPO2, and RSPO3 were significantly reduced in lung cancer patients as compared with normal tissues." (PMID 36645115, 2023). "Consistent with this, administration of RSPO1 to mice increases cell size in the small intestine, and RSPO fusions occur in colon and lung cancer." (PMID 29383135, 2017).
oral mucositis (5 papers, 2009 to 2024). Inflammation of the mucous membranes of any of the structures in the mouth. "More importantly, using Rspo1 appears to be effective during various stages of experimental oral mucositis in mice." (PMID 23882420, 2013). "Rspo1 is effective in both injury and healing phases of oral mucositis in mice by increasing basal layer epithelial cell density in the tongue." (PMID 23882420, 2013). "Interestingly, treatment with Rspo1 is protective for chemotherapy- and radiotherapy-induced oral mucositis." (PMID 38421250, 2024). "Transgenic expression of Rspo1 induces significant enlargement of the small and large intestines, whereas administration of recombinant or adenoviral Rspo1 alleviates intestinal injury and oral mucositis induced by chemoradiotherapy." (PMID 25865226, 2015). "Further experiments demonstrated that Rspo1 prevented mucositis, induced by a chemotherapeutic agent, 5-flurouracil (5-FU), in mice and more recently it was further demonstrated by the same group that Rspo1 protected mice from chemotherapy or radiation-induced oral mucositis." (PMID 19956666, 2009).
osteoporosis (5 papers, 2016 to 2022). A condition of reduced bone mass, with decreased cortical thickness and a decrease in the number and size of the trabeculae of cancellous bone (but normal chemical composition), resulting in increased fracture incidence. "Our findings provided in vivo validation of the therapeutic effect of Rspo1 on unloading-induced bone loss, which revealed another novel potential target for the development of an anabolic therapeutic agent for disuse osteoporosis." (PMID 28272338, 2017). "To determine whether the downregulated Rspo1 in vivo was caused by mechanical unloading per se or by subsequent osteoporosis, we established another classical osteoporosis mouse model and evaluated the Rspo1 expression in ovariectomized (OVX) mice." (PMID 28272338, 2017). "To confirm the in vivo function of Rspo1 on mechanical unloading induced bone loss, we examined the effect of adenovirus-mediated delivery of Rspo1 (ad-Rspo1) in a TS mice model of unloading-induced osteoporosis." (PMID 28272338, 2017). "We not only provided new insight into the mechanism of unloading induced bone loss, but also indicated that Rspo1/Lgr4 could be a potential therapeutic target for treating disuse osteoporosis." (PMID 28272338, 2017). "As a Wnt pathway modulator, R-spondin 1 is secreted by young mesenchymal progenitor cells and promotes bone formation in osteoporosis in response to vibration." (PMID 36568096, 2022). "RSPO1 also promotes vibration-induced bone formation while systemic administration of recombinant RSPO1 in a mouse osteoporosis model resulted in increased bone mass." (PMID 31698687, 2019). "Rspo1/Lgr4 could be a new potential target for the prevention and treatment of disuse osteoporosis in the future." (PMID 28272338, 2017). "Therefore, Rspo1 is valuable in applications of regenerative medicine and holds therapeutic potential for treating diseases such as cancer and osteoporosis." (PMID 27314333, 2016).
squamous cell carcinoma (4 papers, 2012 to 2022). A carcinoma arising from squamous epithelial cells. "The first evidence for RSPO function in skin was through mapping of a familial propensity to palmoplantar hyperkeratosis and squamous cell carcinoma to loss-of-function mutations in RSPO1." (PMID 29416699, 2018). "Notably, RSPO1 loss-of-function mutations were also associated with squamous cell carcinoma (SCC) development in palmoplantar sites in 5 of the 9 patients so far described." (PMID 35854363, 2022). "Loss of RSPO1 in females recessively leads to increased risk of squamous cell carcinoma." (PMID 22615920, 2012). "Humans with hereditary loss of RSPO1 have the skin-thickening condition palmoplantar hyperkeratosis, increased susceptibility to squamous cell carcinoma, and XX sex reversal, but no reported intestinal abnormalities." (PMID 29416699, 2018). "The relationship between R-spondin proteins and cancer was introduced in a study of RSPO1, whereby by regulating keratinocyte proliferation and differentiation, RSPO1 renders keratinocytes prone to squamous cell carcinoma." (PMID 24373193, 2013).